PCNA (proliferating cell nuclear antigen)
Diseases named in the same sentence as PCNA in open-access papers (continued):
Sharing a sentence is not in itself a finding about the gene and the disease.
viral infection (continued). "PCNA-mediated degradation of p21 in the context of viral infection may emerge as an important paradigm for allowing sustained viral replication of DNA polymerase-δ dependent viruses in infected cells." (PMID 24699724, 2014). "In proliferating cells, PCNA’s role within the replication fork can be highjacked by viral pathways and used to enable viral replication; however, the presence of PCNA within neutrophils may allow for an enhanced immune system response to viral infection." (PMID 39205238, 2024). "To confirm that deubiquitination of PCNA and FANCD2 was mediated through USP1 in virus infection, we depleted USP1 using siRNA knockdown." (PMID 41533576, 2026). "However, the induction of mUb-PCNA may also be a host response to virus infection." (PMID 40130902, 2025). "(2021) demonstrated that higher ubiquitination occurs in specific regions of PCNA in SARS-CoV-2 infection, indicating a regulatory mechanism of PCNA by the virus infection." (PMID 35677658, 2022). "Among the NGN2-infected (GFP+) OECs, immunocytochemical analysis showed that PCNA-labeled proliferating cells decreased significantly after viral infection, suggesting that there was no expansion of progenitor cells during the OEC-to-neuron conversion." (PMID 31501413, 2019). "The number of PCNA-positive cells was similar in the two strains of mice at 0, 3, and 5 days after virus infection (data not shown)." (PMID 24676272, 2014). "RNAseq and protein expression analysis ofDDB2,RAD17,PRKDC,PCNA and other ATR pathway markers of infected cells accompanied by time course studies of nascent double stranded chromosomal breaks (i.e. H2AX antibody staining due to viral infection) would provide such evidence." (PMID 33299552, 2020). "Also, cytotoxicity recorded with MCF-7 cells following recombinant virus infection was not comparable with PCNA staining, caspase 3 activity, and Annexin V staining." (PMID 30697531, 2018).
breast tumors (18 papers, 2010 to 2023). "Further, PCNA expression was markedly reduced in tumors treated with dAd/shErbB3, suggesting that the proliferation of breast tumor cells was attenuated similar to those observed in vitro." (PMID 35806132, 2022). "The breast tumor cells of athymic mice from different treatment groups demonstrated nuclear expressions of proliferation marker (PCNA)." (PMID 36358660, 2022). "Berberine exerts chemopreventive effects against DMBA-induced mammary carcinogenesis through downregulating NF-κB and proliferating cell nuclear antigen (PCNA) expression in breast tumors." (PMID 34948368, 2021). "For example, ALDH+ breast tumors display higher proportion of proliferation marker PCNA and a worse clinical outcome while Ki-67+, another classical proliferation marker, is essential for the functional characteristics of BCSC." (PMID 32435546, 2020). "Apparent deregulation of PCNA with increased expression in tissues adjacent to tumors has been observed in some breast tumors." (PMID 32552673, 2020). "The immunohistochemical (IHC) analyses of 2HF treated breast tumors showed decreased levels of proliferation markers Ki67 and PCNA, angiogenesis marker CD31, and increased levels of epithelial differentiation marker E-cadherin." (PMID 29088842, 2017). "Abnormal expression of two NER proteins (RPA, a damage sensor; and PCNA, a progressivity factor) is associated with ER+/HER2- breast tumors." (PMID 27032101, 2016). "PCNA-positive cells that represent proliferating cells in mice xenograft tumors were significantly depleted, and the percentage of PCNA-positive cells were significantly reduced by 5.23 fold in breast tumors of the GE group as compared to the control group." (PMID 23342141, 2013). "The difference in DNMT3b expression between the high β and low β groups of breast tumors became far more modest when the mRNA expression levels were normalized according to those of the cell proliferation marker PCNA (P = 0.060)." (PMID 20830311, 2010). "Similar to our in vivo results using dAd/shErbB3, oAd/shErbB3-treated breast tumors exhibited a markedly lower number of PCNA-positive cells, higher number of TUNEL-positive cells, and decreased level of ErbB3 compared to tumors that were treated with PBS or oAd." (PMID 35806132, 2022).
colitis (18 papers, 2015 to 2026). Inflammation of the colon. "Mice with AOM/DSS colitis exhibited significantly elevated levels of proteins associated with cell death, including PCNA, PTEN, VEGF, COX-2, and STAT-3." (PMID 39598375, 2024). "As a consequence, TNF-α induces the β-catenin target gene expressions including PCNA, Cyclin D1 and c-Myc, thus promoting the colitis-associated tumor development." (PMID 26910375, 2016). "Moreover, even colitis-associated proliferation as examined via western blot analyses against the proliferation marker proliferating cell nuclear antigen (PCNA) was similarly detectable in control and IL-6Rα-deficient samples during colitis." (PMID 29695802, 2018). "Other different markers have been used in immunohistochemical evaluation of colitis model including NF-kB28,34, PCNA and cox-234,46,47, caspase-329,34 and iNOS34,47." (PMID 36228298, 2022). "Immunostaining studies also showed that the expression of PCNA decreased during colitis periods, and β-arr1 KO mice exhibited significantly decreased levels compared with WT mice." (PMID 28432343, 2017). "To determine the involvement of IL-18 in driving IEC proliferation and inhibiting cell death in the Casp11−/− colitis model, we also stained colon sections from the IL-18 rescue experiment for PCNA, BrdU, and TUNEL." (PMID 25548224, 2015). "Previous work revealed that cold exposure alleviates colitis in mice; this study extends that finding by demonstrating that cold exposure enhances intestinal regeneration even in healthy mice, upregulating proliferation markers (Mki67, PCNA, Cyclin D1)." (PMID 41898256, 2026). "On the contrary, Alhagi/MSC significantly downregulated the expression of apoptosis and inflammasome-related proteins, such as NLRP3, BAX, and Caspase3 levels, and weakened the TUNEL positive signal in DSS-induced mouse colitis models, while it increased the PCNA expression levels." (PMID 38612465, 2024). "Taken together, these results demonstrate that inhibition of GABAAR could contribute to maintenance of intestinal integrity in acute colitis by increasing the expression levels of PCNA and Wnt signaling pathway proteins." (PMID 36232509, 2022). "Thus, whereas colitis and colitis-associated proliferation is not affected by IL-6Rα deficiency, tumours of Il6rαKO mice exhibited less PCNA and Ki67 reactivity." (PMID 29695802, 2018). "The researchers found that there was a significant increase of Proliferating Cell Nuclear Antigen (PCNA) and Epidermal Growth Factor (EGF) in the chronic and acute colitis model which was administrated with a dose of 10 mg/kg EC (EC10)." (PMID 28335502, 2017). "Meanwhile, we found that the resident fibroblasts under homeostatic conditions and in the early phase of colitis (A+D-d7) rarely proliferate, as indicated by PCNA-negative staining in both young and ageing mice." (PMID 37553378, 2023). "Moreover, treatment with bicuculline (Bic, a GABAAR inhibitor) increased the levels of PCNA, β−catenin, and TCF4 in mice with colitis." (PMID 36232509, 2022). "We showed that inhibition of GABAAR significantly increased the expression levels of β−catenin, TCF4, and PCNA, suggesting that inhibition of GABAAR may exert protective effects against colitis through the Wnt signaling pathway." (PMID 36232509, 2022). "PCNA, the conserved protein responsible for epithelial proliferation through the Wnt/β–catenin pathway, showed increased levels after BEY administration to the TNBS-induced colitis model comparable to the probiotic strain L. reuteri 22 observed in young chickens." (PMID 35565934, 2022).
liver fibrosis (16 papers, 2011 to 2024). "Finally, ubiquitination of proliferating cell nuclear antigen (PCNA) is induced during CCl4-induced liver fibrosis and associated with the DNA damage response (DDR)." (PMID 33261190, 2020). "Previous studies have shown that ginger supplementation can reduce PCNA expression and prevent the intensification of liver fibrosis." (PMID 37051346, 2023). "In liver diseases, such as NAFLD and cirrhosis, PCNA expression is increased, leading to excessive and uncontrolled proliferation of damaged tissue to replace damaged tissue and liver fibrosis." (PMID 37051346, 2023). "Increased expression of CK-7 and PCNA has been reported in liver transplant patients due to recurrence of liver complications, drug toxicity-induced hypoxia, and liver fibrosis." (PMID 33679236, 2021). "We showed that ubiquitination is relevant for the pathogenesis of CCl4-induced liver fibrosis and several proteins are differentially ubiquitinated under these circumstances, an example being proliferating cell nuclear antigen (PCNA)." (PMID 33261190, 2020). "Taken together, we provide evidence that ubiquitination of proteins involved in several pathways is increased after CCl4-induced liver fibrosis, exemplified by the response to DNA damage and increased ubiquitination of PCNA." (PMID 33261190, 2020). "Other ubiquitinated proteins identified by LC-MS and differentially expressed in CCl4-induced liver fibrosis that cluster with PCNA are two histone families, histone H2a type 1-H (Hist1h2ah, Hist2h2ac) and histone H3.3 (H3f3a)." (PMID 33261190, 2020). "Additionally, other markers exclusive to the proliferating cells, such as MKI67 and PCNA, have been implicated in fibrotic conditions, including IPF, hepatic fibrosis, and cancer." (PMID 38727265, 2024). "The decreased expression for GPC3 simultaneously with the decreased PCNA in the MSCs-transplanted rat livers proved the potential of MSCs in preventing progression of preneoplastic transformation initially triggered by CCl4 liver fibrosis." (PMID 31781620, 2019). "To document that resolution of liver fibrosis is associated with concomitant reduction of HSCs activation and global cellular proliferation we performed immunohistochemical analysis of α-SMA, a marker of HSC activation, and PCNA, a marker of cell proliferation in liver tissues." (PMID 25380300, 2014). "Western blot analysis showed an extensive increase in the expression of profibrotic mediators α-SMA, collagen I, VEGF and proliferating cell nuclear antigen (PCNA) in CCl4- and BDL-induced liver fibrosis." (PMID 36514072, 2022). "Here, we also showed that H19 deficiency reduced the BDL-induced hyperplasia of cholangiocytes and ameliorated liver fibrosis, as indicated by downregulation of the protein expression of CK19, PCNA, α-SMA, and collagen I." (PMID 34168124, 2021). "The expression levels of several hepatic fibrosis markers such as alpha smooth muscle actin (αSMA), collagen type 1 alpha 1 chain (Col1A1), fibronectin 1 (FN1), PCNA and tissue inhibitor of metalloprotease 1 (TIMP1) were tested by RT-qPCR." (PMID 29125588, 2017). "To further explore the mechanism of EXE suppressing hepatic fibrosis, we performed immunohistochemical staining for α-SMA, a marker of HSC activation, and PCNA, a marker of cell proliferation in the rat liver samples from both EXE-treated and control groups." (PMID 29464186, 2017). "Compared with the alcohol group, ADAM8 mRNA and protein expression, cell viability, and the expression of liver fibrosis markers and MAPK signaling pathway-related factors (p-ERK1/2, PCNA, Bcl-2, p-c-Jun, TGFβ1, p–p38 MAPK and HSP27) reduced significantly in the si-ADAM8-2 group." (PMID 39407108, 2024). "Gallic acid exhibited the ability to inhibit HSCs cell proliferation in a dose-dependent and time-dependent manner, decrease α-SMA expression, lower the levels of liver injury markers such as PCNA, PDGF-BB, TIMP-1, HP, and reduce collagen deposition in a rat model of liver fibrosis." (PMID 39185304, 2024).
liver fibrosis (continued). "BI 113823 significantly reduced the expression of fibrotic proteins α-SMA, collagens 1, 3, 4, and profibrotic growth factors PDGF, TGFβ, CTGF, VEGF, proliferating cell nuclear antigen; and reduced hepatic Akt phosphorylation in CCl4- and BDL-induced liver fibrosis." (PMID 36514072, 2022).
non-small cell lung carcinoma (16 papers, 2000 to 2026). A group of at least three distinct histological types of lung cancer, including non-small cell squamous cell carcinoma, adenocarcinoma, and large cell carcinoma. "In a concentration-dependent manner, T4 induced PCNA accumulation in NCI-H522 non-small cell lung carcinoma cells." (PMID 22132110, 2011). "When non-small cell carcinoma NCI-H522 cells were treated with thyroid hormone (T4 or T3) for 24 h in the presence or absence of 0.05–5 nM ICI, both hormones caused activation of ERK1/2 and PCNA accumulation." (PMID 22132110, 2011). "In addition, the proliferative factors proliferating cell nuclear antigen and cyclin A were reduced compared to the sensitive non-small cell lung carcinoma." (PMID 12177790, 2002). "A multivariate analysis (Cox model) of the cellular and clinical prognostic factors indicated that stage, lymph node involvement, Fas, PCNA and cyclin A are the most important prognostic factors for the clinical outcome of patients with non-small-cell lung carcinomas." (PMID 10817513, 2000). "Bioinformatic analyses have demonstrated that EGFR, KDR, FN1, TGFB1 as well as PCNA are interacting with VEGF-A and are involved in non-small cell lung cancer tumorigenesis." (PMID 35252204, 2022). "T4 at physiologic concentrations and T3 at supraphysiologic concentrations increase abundance of proliferating cell nuclear antigen (PCNA) and ERK1/2 activation, markers of cell proliferation, in small cell and non-small cells lung cancer models." (PMID 30814976, 2019).
oral cancer (16 papers, 2010 to 2026). "The antiproliferative activity of β-caryophyllene in KB oral cancer cells was found to be also mediated by a reduced expression of PCNA (proliferating cell nuclear antigen) and cyclin D1, which are required for tumor cell growth and survival." (PMID 33081075, 2020). "Collectively, the higher expression intensity of PCNA and Ki-67 indicating the proliferation activity and malignancy of oral cancer cells was dramatically decreased by AGA treatment." (PMID 33142749, 2020). "In this study, we found that melatonin impaired the proliferation and apoptosis resistance of oral cancer cells by inactivating ROS-dependent Akt signaling, involving in downregulation of cyclin D1, PCNA, and Bcl-2 and upregulation of Bax." (PMID 29725496, 2018). "In this study, treatment with ROS scavenger NAC reduced the levels of p-Akt, cyclin D1, PCNA, and Bcl-2 and increased the expression of Bax in oral cancer cells." (PMID 29725496, 2018). "The high expression of typical biomarkers of cell proliferation, such as cyclin D1 and PCNA, induces the propagation of unrepaired DNA damage, accumulation of genetic errors and a selective growth advantage for altered cells, thereby promoting oral cancer progression." (PMID 29725496, 2018). "LUCAT1 promotes cell invasion in several cancer types, including gastric, liver, and oral cancer cells, by modulating YWHAZ, Annexin A2, or PCNA." (PMID 36980216, 2023). "By decreasing the expression level of COX-2 and proliferating cell nuclear antigen (PCNA), L. salivarius intervention had significant inhibitory effects on tumor growth of oral cancer." (PMID 34992527, 2021). "Furthermore, astaxanthin was observed to inhibit cell divisions in a hamster model of oral cancer via the regulation of cyclin D1 action, inhibiting JAK/STAT-3 kinases and proliferating cell nuclear antigen (PCNA)." (PMID 35276890, 2022). "Inhibited rat oral cancer progression through regulating the expression of COX-2 and PCNA." (PMID 34992527, 2021). "Collectively, VEGF, PCNA and MMP9 may modulate the proliferation, migration, and invasion of oral cancer cells under the regulation of SYK." (PMID 29137391, 2017). "Downregulation of the protein expression of survivin, X chromosome-linked inhibitor of apoptosis (XIAP), proliferating cell nuclear antigen (PCNA), iNOS and COX-2 and increased apoptotic activity suggested that TSL therapy might aid the prevention of oral cancer." (PMID 38338461, 2024).
bladder cancer (14 papers, 1995 to 2025). "Initially, we evaluated the association of the expression levels among FN, CIP2A and PCNA in bladder cancer tissue samples (n = 68)." (PMID 28521777, 2017). "Another phase II preoperative randomized controlled trial involving patients with bladder cancer showed EGCG-rich green tea extract significantly reduced biological markers of bladder cancer tissue, including PCNA and clusterin, which are associated with tumor proliferation, invasion, and migration." (PMID 37292151, 2023). "Capsaicin was shown to activate transient receptor potential vanilloid 1 (TRPV1) to prevent the nuclear translocation of proliferating cell nuclear antigen, and was found to inhibit cell growth in a bladder cancer cell line in which TRPV1 is highly expressed." (PMID 34512323, 2021). "Here we demonstrate the positive correlations of stromal FN with CIP2A and PCNA expression in a cohort human bladder cancer tissues." (PMID 28521777, 2017). "In this study, we found that stromal FN expression correlated positively with the levels of CIP2A and PCNA in bladder cancer tissues." (PMID 28521777, 2017). "We found CCEPR upregulates the expression of PCNA and serves as a key regulator in bladder cancer development and progression." (PMID 28574830, 2017). "The correlations of stromal FN with CIP2A and proliferating cell nuclear antigen (PCNA) expression were analyzed in a cohort bladder cancer patients." (PMID 28521777, 2017). "Additionally, n6-methyladenosine enhances the translation of ENO1 by inhibiting PCNA ubiquitination, thereby facilitating the progression of bladder cancer." (PMID 40771930, 2025). "Additionally, the correlation between CENPW expression and CDK1, CCNB1, and PCNA was further investigated in 10 bladder cancer tissue samples." (PMID 38213721, 2024). "Similarly, PLCE1 knockdown in bladder cancer reduces proliferating cell nuclear antigen and cyclin D1 in the bladder tumor xenograft, leading to significant inhibition of cell proliferation and cell cycle arrest." (PMID 26657507, 2016). "In addition, the IHC staining indicated decreased expression pattern of Ki-67 and PCNA in miR-877-3p-overexpressing tumor tissues, which confirmed that miR-877-3p negatively regulate the growth of bladder cancer." (PMID 27429046, 2016). "Targeting PCNA with ATX-101 was previously shown to reduce Akt signaling in human monocytes and in bladder cancer cells." (PMID 35053455, 2022). "The following western blotting assays further strengthened the evidence linking FN with CIP2A in bladder cancer tissues (n = 68), meanwhile, Spearman’s correlation analysis revealed the positive correlation between the gray value of CIP2A and PCNA (r = 0.459, P < 0.001)." (PMID 28521777, 2017).